IL33 (interleukin 33)
Diseases named in the same sentence as IL33 in open-access papers (continued):
Sharing a sentence is not in itself a finding about the gene and the disease.
tumor (continued). "There was a significant increase in the number of CD11b+ myeloid cells, T cells, NKT, and NK cells present in the tumor-bearing hemisphere of IL-33+ vs. IL-33− 1492 syngeneic mice." (PMID 33020472, 2020). "The authors went on to demonstrate that ILC2 expanded in the presence of IL-33 inhibited the anti-tumor effect of NK cells." (PMID 33371444, 2020). "Adding to this complexity is the promiscuous nature by which MCs respond to cytokines other than IL33 and release chemotactic factors that recruit immune cells into the tumor microenvironment." (PMID 32719677, 2020). "A similar prognostic impact was described in another retrospective study that also assessed IL33 tumor expression via immunohistochemical staining." (PMID 32707675, 2020). "In contrast, neutralizing IL-33 or ST2 by administration of antibodies remarkably decreases the density of ST2-positive Tregs inside tumor masses in CRC-bearing mice." (PMID 32246094, 2020). "In vivo interference with LDHA in B16.F10 tumors or administration of IL-33 to tumor-bearing mice increased the number of intratumoral ILC2 and restored ILC2 ability to contrast tumor progression." (PMID 33329534, 2020). "IL-33-dependent tumor-infiltrating ILC2s mobilize from lung and recruit DCs to promote the adaptive T-cell response." (PMID 32117199, 2019). "Accumulating data demonstrate that IL-33 plays a vital role during the process of tumour occurrence and development." (PMID 31889095, 2019). "In the tumor, IL-33 distribution is heterogeneous among patients, observing both nuclear and cytoplasmic staining in tumor epithelial cells, with stromal staining in fibroblast-like cells, mononuclear cells and endothelium." (PMID 31281317, 2019). "Pro-tumor: Accumulation of ILC2s and their cytokines, IL-33 and IL-4 contribute to immune-suppressive environment." (PMID 32117199, 2019). "By using a panel of tumor cell lines, we show that IL-33 promotes tumoricidal functions of eosinophils in vitro and in vivo in a cell adhesion-dependent manner, through the integrin CD11b/CD18 and by inducing lytic granule convergence to the immune synapse." (PMID 31717819, 2019). "It was found that IL-33 content increases in left-sided CRC patients with lymphatic metastasis, with localization in tumor epithelia associated with abundant desmoplasia." (PMID 31281317, 2019). "At early stages, tumor IL-33 levels were lower than its corresponding non-tumor distant tissue (p = 0.02 and 0.03 for TNM stage 1 and 2), however, stage 3 tumor tissue show increased IL-33 compared to stage 1 (p = 0.03)." (PMID 31281317, 2019). "This hierarchization shows a close relationship between variations of tumor and stromal IL-33 content together with stromal ST2 in relation to desmoplasia." (PMID 31281317, 2019). "Activation of IL-33 stimulates various signaling pathways implicating in tumor initiation, and p38 MAPK is one of the critical downstream targets of IL-33." (PMID 30691509, 2019). "We show that IL-33 recruits eosinophils indirectly, via stimulation of tumor cell-derived chemokines, while it activates eosinophils directly, up-regulating CD69, the adhesion molecules ICAM-1 and CD11b/CD18, and the degranulation marker CD63." (PMID 31717819, 2019). "Tumor formation in this model appears to require IL-6, as this can be substituted for IL-33, and tumor formation is completely eliminated in IL-6 knockout mice." (PMID 30815737, 2019). "We therefore focused on IL-33 as a potential tumor-derived activator of mast cells, because IL-33 was reported to serve as an alarmin that is generated and released by necrotic cells, and that triggers mast cell degranulation." (PMID 31227713, 2019). "Several literature works have highlighted the broad expression of IL-33 in normal, tumor, and chronically inflamed human tissues, confirming their significant expression in the kidneys." (PMID 30769901, 2019).
tumor (continued). "In tumor-bearing mice, IL-33 induced substantial accumulation of degranulating eosinophils within tumor necrotic areas, indicating cytotoxic activity in vivo." (PMID 31717819, 2019). "IL-33 promotes ILC2 secretion of CXCR2 ligands that bind to CXCR2-expressing tumor cells, reinforcing tumor cell-specific apoptosis independent of adaptive immunity." (PMID 32117199, 2019). "In CRC, the IL-33/ST2 axis activates the tumor stroma fibroblasts promoting polyp formation in Adenomatous Poliposis Coli (APC)Min/+ mice model." (PMID 31281317, 2019). "In murine models of CRC, increased IL-33 levels in tumor cells induce greater hepatic metastasis, increase tumor size and, therefore, lower survival rate." (PMID 31281317, 2019). "Tumor development results in down-regulation of IL-33 in epithelial cells but up-regulation of IL-33 in the tumor stroma and serum." (PMID 31238901, 2019). "In a murine lymphoma model, production of IL-33 within the tumor locally enhances the number of ILC2s with potent anti-tumor activity." (PMID 31024531, 2019). "Blocking of CD11b/CD18 signaling significantly reduced IL-33-activated eosinophils’ binding and subsequent killing of tumor cells, indicating a crucial role for this integrin in triggering degranulation." (PMID 31717819, 2019). "We initially reported that IL-33 inhibits tumor growth and pulmonary metastasis in vivo in an eosinophil-dependent manner." (PMID 31717819, 2019). "Expression of ST2L on CD8+ T cells represents a mechanism regulating IL-33 bioactivity on a cellular level also in the context of tumor immunity, although the function of IL-33 in tumor immunity is currently controversially discussed." (PMID 31396219, 2019). "Recent data showed the implication of the IL-33/suppressor of tumorigenicity 2 (ST2) axis in tumor development and metastasis." (PMID 31130612, 2019). "The metastatic LN presents variable α-SMA (desmoplasia) and IL-33 is present in cells with fibroblast-like morphology in areas with high desmoplasia and tumor invading cells." (PMID 31281317, 2019). "IL-33 also accelerated tumor growth and metastasis development, by sustaining the ILC2/M-MDSC/Tregs immunosuppressive axis as well as by promoting neovascularization." (PMID 31024531, 2019). "Here again, we found that tumor IL-33 levels from left-sided CRC patients were increased in those with LN metastasis (p = 0.04)." (PMID 31281317, 2019). "In the B16 melanoma model, it was also recently shown that IL-33 induced NK cells mediated anti-tumor immune responses in parallel with the expansion and activation of ILC2s via its receptor ST2." (PMID 31024531, 2019). "Dual immunofluorescence staining of EPX and cleaved caspase-3 revealed juxtaposition of apoptotic tumor cells to intratumoral eosinophils with polarized EPX (arrow) in IL-33 treated mice." (PMID 31717819, 2019). "Taken together, these data demonstrate that IL-33 stimulates both adhesions of eosinophils to tumor cells and convergence of granules to the EO-tumor cell synapses, suggesting degranulation upon cell contact." (PMID 31717819, 2019). "Anti-tumor: IL-33 stimulates ILC2s to secrete CXCR2 ligands that bind to CXCR2-expressing tumor cells to induce tumor cell-specific apoptosis independently of adaptive immunity." (PMID 32117199, 2019). "Although the role of IL-33 in tumor immunity is discussed controversially, IL-33 detected in serum has been proposed as a prognostic biomarker for different cancer diseases." (PMID 31396219, 2019). "The authors show that mast cells are more abundant than ILC2s in gastric tumors and secrete macrophage-chemoattractant colony-stimulating factor 2 (CSF2), CCL3, and IL-6 in response to activation by tumor-derived IL-33." (PMID 31849977, 2019). "Those cells can be modulated in an IL-33 dependent fashion to generate regulatory or effector T cells, implicating new findings with relevance for tumor immune therapy." (PMID 31396219, 2019).
tumor (continued). "In fact, we observed substantial expression of granzyme-B and EPX in tumor-infiltrating EO induced by in vivo exposure to IL-33, at variance with control mice." (PMID 31717819, 2019). "We demonstrate that activation by IL-33 increases eosinophil cytotoxicity against several tumor cell lines via the induction of apoptosis." (PMID 31717819, 2019). "Here, we analyzed the mechanisms by which IL-33 mediates tumor infiltration and antitumor activities of eosinophils." (PMID 31717819, 2019). "We found similar levels between tumor IL-33 compared to distant healthy tissue, as well as IL-33 levels according to TNM staging." (PMID 31281317, 2019). "Right-sided tumor IL-33 and ST2 levels were similar in those patients with regional LN metastasis compared to those without metastasis (respectively)." (PMID 31281317, 2019). "ILC2 antitumor activity under IL-33 stimulation is also involved in recruiting eosinophils to limit tumor growth and in shaping chemokine profiles in the TME under IL-5 release." (PMID 32117199, 2019). "Collectively, these data indicate that when high levels of IL-33 are administered, potent anti-tumor effects are observed." (PMID 31231372, 2019). "Among the different TME mediators, IL-33 has been reported to inhibit tumor growth in a melanoma mouse model, by stimulating the anti-tumor activity of CD8+ T cells and natural killer (NK) cells." (PMID 31849977, 2019). "The cancer Osaka thyroid oncogene (COT) is another kinase activated by IL-33, leading to tumor progression." (PMID 31130612, 2019). "An IL-33 blockade restricts NSCLC outgrowth, abrogates polarization of M2 tumor-associated macrophages (TAMs), and reduces accumulations of Treg cells in tumor tissues, thus representing an effective and promising strategy for NSCLC treatment." (PMID 31130612, 2019). "Tumor cell death was further confirmed by a significant reduction of tumor-covered area after 24 h co-culture with IL-33 EO." (PMID 31717819, 2019). "In most cases, IL-33 is overexpressed in tumor cells, whereas, conversely, a high quantity rate of alarmin in patients’ blood coincides with reduced tumor progression." (PMID 31130612, 2019). "The IL-33/ST2 axis is emerging as a powerful modulator of the tumor microenvironment (TME) by recruiting immune cells, able to modify the TME, supporting malignant proliferation or improving antitumor immunity." (PMID 31130612, 2019). "In animal models, transgenic expression of IL-33 augmented the accumulation of cytotoxic NK cells to the tumor tissue that inhibited metastasis formation." (PMID 31652497, 2019). "The linear signaling cascade identified here comprising IL-11/IL-33/mast cells/macrophages/tumor cells should provide complementary molecular and cellular targets for the development of improved cancer therapies." (PMID 31227713, 2019). "In this view, expression of IL-33 has been reported in several human tumors, although its correlation with tumor progression is controversial." (PMID 31717819, 2019). "In a cancer model mimicking the tumor microenvironment, IL-33 directly affected the survival of tumor cells by activation of mTOR." (PMID 31396219, 2019). "To evaluate the involvement of adhesion molecules in the formation of cell conjugates among eosinophils and tumor cells, we carried out CLSM of IL-33 and IL-5 EO in co-culture with tumor cells." (PMID 31717819, 2019). "Together, these findings indicate that IL-33 greatly enhances the tumoricidal properties of eosinophils resulting in tumor growth suppression in vivo." (PMID 31717819, 2019). "ILC2s impair IL-33-mediated tumor suppression by antagonizing the NK cell function during tumor growth via CD73 independently of adaptive immunity in a melanoma mouse model." (PMID 32117199, 2019). "To extend these findings, we tested the tumoricidal activity of IL-33 EO against four different tumor cell lines (B16, MC38, MCA205, and TC-1)." (PMID 31717819, 2019).
tumor (continued). "Given the dichotomous activity of IL-33 in tumor biology, timing of anti-IL-33 signaling therapy will be crucial." (PMID 31227713, 2019). "IL-33 also triggers CXCR2 upregulation in tumor cell surface through a dysfunctional angiogenesis leading to ROS production." (PMID 31024531, 2019). "Analysis of Siglec-F+PKH26+ cells over the total of PKH26+ tumor cells revealed that IL-33 EO formed increased numbers of cell conjugates with tumor cells, as compared to IL-5 EO." (PMID 31717819, 2019). "CLSM analysis confirmed the effective establishment of cell conjugates among PKH26+ eosinophils and PKH67+ tumor cells, with notably increased incidence in IL-33 EO." (PMID 31717819, 2019). "In the human papilloma virus-associated cancer model, IL-33 increases antigen-specific CD8+ T-cell responses and induces tumor regression." (PMID 31509992, 2019). "ST2 is secreted into the tumor environment as a decoy receptor, resulting in competitive inhibition of IL-33/ST2 autocrine and paracrine signals." (PMID 31186061, 2019). "Our data provide mechanistic insights into eosinophil anti-tumor activities stimulated by IL-33 that involve cell contact and directional secretion of granules toward target tumor cells enhancing killing efficiency." (PMID 31717819, 2019). "An association between IL-33 immunoreactivity in the tumor epithelium of patients with metastatic CRC and shorter survival has been reported, suggesting that tumor expression of IL-33 would be clinically important in its progression." (PMID 31281317, 2019). "In fact, IL-33 promoted eosinophil migration to the tumor indirectly, via induction of the chemokines CCL5 and CCL24/eotaxin-2 by tumor cells themselves." (PMID 31717819, 2019). "NSCLC-derived IL-33 supports tumor growth in an autocrine manner and educates immune surveillance in tumor microenvironments, favoring the immune escape of tumor cells." (PMID 31130612, 2019). "In line with the reported storage of IL-33 protein in vesicles, we detected increased levels of Il33 mRNA and IL-33 protein in whole tumor tissue." (PMID 31227713, 2019). "Based on our previous findings indicating inactivity of IL-33 in blood, we concluded that the role of IL-33 in adaptive tumor immunity would be limited to infiltrated or tissue resident effector CD8+ T lymphocytes." (PMID 31396219, 2019). "IL-33 expression in tumor cells increases immunogenicity and promotes type 1 antitumor immune responses." (PMID 31238901, 2019). "Our genetic analysis reveals a linear signaling axis initiated by tumor epithelial-derived IL-33 that activates mast cells to produce a chemotactic cytokine expression signature." (PMID 31227713, 2019). "CD11b/CD18 and, to a minor extent, ICAM-1 significantly polarized to the IL-33 EO-tumor cell synapses, whereas they were expressed evenly on the cell membrane of IL-5 EO conjugated with target tumor cells." (PMID 31717819, 2019). "The heterogeneity of tumor blood flow and growing tumor mass cause necrotic areas within tumor tissue or tumoral HEV, which represent sources of IL-33." (PMID 31396219, 2019). "In recent years, increasing evidence has demonstrated that IL-33 is a vital component of tumour occurrence and advance, for instance, antitumour immunity, tumour growth, tumour metastasis, and tumour invasion." (PMID 31889095, 2019). "IL-33 has also been shown to promote tumor cell growth, colony formation and expression of Ki-67 and proliferating cell nuclear antigen (PCNA) in a PGE2 dependant manner." (PMID 31231372, 2019). "Strikingly, blocking of CD11b/CD18 in IL-33 EO significantly inhibited both tumor cell adhesion and killing, demonstrating a crucial role of this integrin in these processes." (PMID 31717819, 2019). "The difference in IL-33 expression between primary and metastatic tumours in our study model enabled examination of the involvement of ILC2s and IL-33 in cancer progression." (PMID 29440650, 2018).
tumor (continued). "Tumor expression of IL-33 was also reported to inhibit tumor growth and favor tumor eradication by modifying the tumor microenvironment through CD8+ T cells." (PMID 30619376, 2018). "Yang and collaborators showed that TAM are recruited by IL-33 in the TME, and IL-33-stimulated TAM can increase intravasation of tumor cells into the circulation at the early stages of metastasis." (PMID 30416507, 2018). "In IL-33-treated mice, intra-tumor NKp46(+) NKG2D(+) and NKp46(+) FasL(+) cells were markedly reduced, while PBS-treated ST2-deficient mice had increased frequencies of these tumoricidal NK cells compared to that in untreated wild-type mice." (PMID 30619376, 2018). "Since inflammation is another important component in malignancies, it drove more studies on how IL-33 plays roles in improving cancerous surveillance and immunity against tumor." (PMID 30619376, 2018). "Altogether, these data indicated that the IL-33/ST2L pathway is involvedin CRC development in tumor-bearing mouse model." (PMID 29950152, 2018). "Both tumor and stromal cells have been shown to express IL-33, ST2L, and sST2 thus IL-33/ST2 signaling can potentially function in an autocrine or paracrine fashion to stimulate tumor cells as well as stromal cells in the TME." (PMID 30205617, 2018). "We also demonstrated that re-introducing IL-33 into metastatic murine tumours increases expression of antigen processing components including TAP-1 and MHC-I surface expression and augments cytotoxic T cell (CTL) immune recognition." (PMID 29440650, 2018). "Expression of the housekeeping genes between the tumour cell samples (A9+vector; A9+IL-33; TC1+vector) were normalized to the transcription levels seen in the A9+vector samples." (PMID 29440650, 2018). "The role of IL-33 in tumor progression has been illustrated elsewhere, with overexpression of IL-33 identified as a diagnostic and prognostic marker for several types of cancer." (PMID 30515150, 2018). "Under pro-tumorigenic conditions, IL-33 directed the recruitment of tumor promoting inflammatory immune cells such as MDSCs, mast cells, macrophages, and Tregs." (PMID 30205617, 2018). "Given that ILC2 are developmentally and functionally dependent on the presence of IL-33, we compared the transcriptional profile of metastatic tumour cells before and after genetic modification with IL-33 gene." (PMID 29440650, 2018). "In our previous study, we found that tumoral expression of IL-33 greatly inhibited tumor growth and metastasis." (PMID 29499051, 2018). "Altogether, these resultssuggested that IL-33 induced the recruitment of tumor-infiltrating ST2L+Tregcells that contributed to the development of CRC." (PMID 29950152, 2018). "It has been suggested that IL-33 has opposing effects in tumor immunity depending on its local concentration." (PMID 30483263, 2018). "IL-33 promoted tumor growth, development of lung and liver metastases, intratumoral cell proliferation and neovascularisation." (PMID 29587679, 2018). "Based on our data, we suggest that IL-33/ST2 signaling modulate immune cells infiltration in the tumor microenvironment and NK cells activity favoring tumor development." (PMID 30112116, 2018). "Upregulation of IL-33 has been reported in tumor growth and metastasis in lung, colorectal, and gastric cancer." (PMID 30631327, 2018). "This increase in the numbers of ILC2s paralleled the reduced growth rate seen by both the primary TC1 or metastatic A9+IL-33 tumours, as compared to the metastatic A9 tumours in mice transplanted with WT BM." (PMID 29440650, 2018). "IL-33 is a potent pro-angiogenic factor that markedly enhances angiogenesis during tumor development." (PMID 30547011, 2018). "IL-33 is also able to recruit large amounts of type 2 innate lymphoid cells to the tumor lesions and inhibit tumor growth." (PMID 29896199, 2018). "Here, we will review the biological role of IL-33 affecting immune responses with particular emphasis on anti-tumor immunity." (PMID 30483263, 2018).